HIF1A (hypoxia inducible factor 1 subunit alpha)
Diseases named in the same sentence as HIF1A in open-access papers (continued):
Sharing a sentence is not in itself a finding about the gene and the disease.
tumor (continued). "This is the first study to show that GBE1 is transcriptionally regulated by HIF1α and that GBE1, a critical downstream effector of HIF1α, affects tumor progression." (PMID 32439898, 2020). "Previous studies identified C-1311 as a multitargeted compound, which blocks activity of topoisomerase II, HIF-1α/VEGF signalling, tumour angiogenesis, and FLT3 receptor tyrosine kinase FLT3." (PMID 32825120, 2020). "There was a positive correlation between SP1 and HIF-1α protein expression in ESCC samples, and SP1 expression was also correlated with tumor metastasis, recurrence and poor prognosis." (PMID 31892989, 2020). "It is now accepted that VEGF expression is mediated by HIF-1α during hypoxia, and the expression of HIF-1α directly correlates with VEGF expression and tumor vascularity in several tumors." (PMID 31947661, 2020). "The implantation of a xenograft tumor also shows that FOXO1 downregulation promotes tumor growth, increases the microvessel area, and raises HIF-1α and VEGF levels." (PMID 32629884, 2020). "A previous study has demonstrated that UCHL1 stabilized HIF-1α by abrogating the von Hippel-Lindau-mediated ubiquitination of HIF-1α, which subsequently promoted tumor metastasis." (PMID 32483437, 2020). "To confirm the clinical relevance of HIF‐1α and STAT3 interaction, we collected 20 tumour samples from TNBC patients." (PMID 32065498, 2020). "Current studies suggest that HIF-1α can induce the expression of CD24 at the transcriptional level, which further points out the importance of hypoxia and the expression of CD24 for tumor immune escape." (PMID 32765491, 2020). "HIF-1α can also regulate the interaction of BCSC with the microenvironment, placing it in a key position in maintenance of the tumor stem phenotype and suppression of immune response." (PMID 32850424, 2020). "Both HIF-1α and VEGF positively correlated with tumor stage and negatively correlated with patients survival." (PMID 32354000, 2020). "Enumeration of these four classes across multiple micrographs per tumor type revealed a statistically significant reduction in double-positive (MKI67+,HIF1a+) cells in ALK4L75A-Fc-expressing tumors." (PMID 33187540, 2020). "Our study also showed that alterations in HIF1α and ME1 expression occurred concomitantly, suggesting a relationship between tumor budding and hypoxia." (PMID 32998265, 2020). "The results demonstrated that Man-3DG and Man-6DG suppress the growth, migration, tumor angiogenesis, and cancer stemness of HCC through the inhibition of c-Met signaling and expression of HIF-1α and stemness markers." (PMID 32516967, 2020). "Our results showed that (a) PRKAR2B enhances PCa cell glycolysis, (b) PRKAR2B is able to upregulate HIF‐1α protein level, (c) HIF‐1α transcriptionally induces PRKAR2B expression in PCa; (d) PRKAR2B‐mediated tumour growth in PCa cells is glycolysis‐dependent." (PMID 33025691, 2020). "We established a tumor microenvironment of BC cells in vitro and found that hypoxia exposure promoted BC cell migration and activated HMGB1/HIF‐1α signaling pathway." (PMID 32436353, 2020). "Studies have found that overexpression of miR-21 in Du145 human prostate cancer cells increased the expression of HIF-1α and VEGF, and induced tumor angiogenesis." (PMID 35006436, 2020). "In rapidly growing cancers, hypoxic conditions greatly activate the expression of HIF-1α transcription factor, which in turn triggers VEGF protein expression in tumour cells." (PMID 33076322, 2020). "Our results also point that the GRK2/HuR/ HIF1α axis is involved in modulating the expression of VEGF-C, a critical factor for remodeling the lymphatic network and tumor cell dissemination." (PMID 32413989, 2020). "HIF-1α is the most important regulator of GLUT3, and it can promote the “Warburg effect” where tumor cells are guaranteed a sufficient supply of energy substances under hypoxic and ischemic conditions." (PMID 32908869, 2020).
tumor (continued). "The stabilization of hypoxia-inducible factors HIF-1α and HIF-2α has been detected in hypoxic macrophages of PDAC as tumor progression." (PMID 33505964, 2020). "The IHC staining results also confirmed that the protein levels of HIF1A and LDHA were higher in tumor tissues, than in normal tissues." (PMID 32152275, 2020). "This study validated the relationship between HIF-1α expression and tumor metastasis in ESCC and the effect of HIF-1α on the prognosis of patients with ESCC." (PMID 31892989, 2020). "We also found that nicotine enhanced expression levels of YAP1 and HIF1A in a dose-dependent manner, both of which induce EMT and tumor growth in PDAC cells in vitro and in murine xenograft models." (PMID 32894161, 2020). "There are also reports showing that AMPK‐HDAC5 pathway facilitates accumulation of HIF‐1a in the nucleus and functional activation of HIF‐1 by deacetylating Hsp70 in tumour cells." (PMID 32519437, 2020). "A cadherin switch and an intermediate filaments rearrangement within primary site tumor cells together with the expression of the EMT-related transcription factors TWIST-1, ZEB-1, and HIF-1α were observed." (PMID 33297475, 2020). "HIF-1α and VEGF are major regulators of angiogenesis in the tumor microenvironment and have a crucial role in tumor progression." (PMID 31947661, 2020). "Pro-EGCG such as octaacetate or peracetate-protected EGCG suppressed xenograft tumor growth, inhibited tumor angiogenesis, and reduced the expression of vascular endothelial growth factor A (VEGFA) and HIF1α by the PI3K/AKT/mTOR signaling pathway." (PMID 33113766, 2020). "Here, we analyzed hypoxia-regulated molecules such as HIF1α and BNIP3 that are commonly up-regulated during tumor progression." (PMID 32668709, 2020). "The results showed that the gene expression of Hif1α, VEGFR and VEGFR2 started at the early stage when the volume of the tumor is less than 100 mm3, then went up dramatically in advanced and end stage as compared with healthy ones." (PMID 32373503, 2020). "Many studies on human malignant neoplasms have reported that HIF-1α and VEGFA induce tumor angiogenesis." (PMID 32382013, 2020). "To optimize the likelihood of tissue-based tumor hypoxia detection, we created a hypoxia score by combining the scores of the immunohistochemical staining for GLUT1 and the binarized HIF1a, both known to be upregulated under hypoxic conditions." (PMID 32984043, 2020). "HIF1A, a subunit of hypoxia-inducible factor-1 (HIF1), has been reported to be involved in tumor progression." (PMID 33067424, 2020). "GDF15 is expressed much more in tumor tissues of CRC patients and displays positive correlations with CHOP and HIF1α in mRNA levels." (PMID 32076610, 2020). "Upregulated HIF-1α expression was found in up to 55% of CRC tissue biopsies and correlates with tumor stage." (PMID 32610612, 2020). "Through HIF-1α activation, hypoxia induces the expression of vascular endothelial growth factor (VEGF), which promotes tumor angiogenesis." (PMID 32775303, 2020). "Hypoxia-inducible factors, including HIF-1α and HIF-2α, are main regulators in adaptation to hypoxia and nutrient deprivation during tumor progression." (PMID 33489906, 2020). "On the other hand, STAT1 can inhibit angiogenesis by inhibiting hypoxia inducible factor alpha (HIF-1α) and vascular endothelial growth factor (VEGF-A), thereby promoting a decrease in tumor growth." (PMID 33076315, 2020). "Although the underlying mechanism regarding the hot or cold tumour immune status remains unclear to date, we considered OSCC tumours with high 18F-FDG-uptake to have cold tumour characteristics as low PD-L1 and low CD8+TILs partially by the activation of the HIF-1A/GLUT1/EMT axis." (PMID 32238919, 2020).
tumor (continued). "Further, researchers found that COMM domain-containing 1 (COMMD1) disrupted the dimerization of HIF-1α and HIF-1β, which then inhibited NF-κB mediated gene expression and tumor cell invasion." (PMID 32127518, 2020). "Hypoxia inducible factor-1 alpha (HIF-1α) signaling is a central axis that activates oncogenic signaling and acts as a metabolic switch in endothelial cell (EC) driven tumor angiogenesis." (PMID 32012744, 2020). "Among these cell lines, HT29 cell line was highly expressed with FBX8, SOX-2 and SOX-2, and CD44, while quite weakly expressed with CDK4, HIF-1α, and c-Myc, indicating that HT29 cell line was an appropriate model to study tumor dormancy." (PMID 32796813, 2020). "Noteworthy, numerous neoplastic cells were scattered throughout the tumor area and expressed the EMT-related transcription factors TWIST-1, ZEB-1, and HIF-1α." (PMID 33297475, 2020). "The results of the tissue microarray including 30 LUAD samples showed that the expression of the hypoxia-relevant molecules HIF1α and vascular endothelial growth factor (VEGF) was significantly higher in the tumor tissues than it was in the peritumor tissues." (PMID 32439898, 2020). "Activation of STAT3 contributes to hypoxia-inducible factor 1 alpha (HIF-1α) and vascular endothelial growth factor (VEGF) expression in tumor cells, while VEGF in turn activates STAT3 in endothelial cells." (PMID 32664527, 2020). "As the centre of the tumour islands showing higher expression of HIF-1α curiously promote higher VEGF expression in the same region, as well as a higher expression of VEGFR-2 in tumour cells." (PMID 33067558, 2020). "ATP is secreted in response to hypoxia, which in turn induces the expression of HIF-1α, which drives the expression of CD39 and CD73 on tumor cells and on several immune components of the TME." (PMID 32585931, 2020). "Other pro-invasive factors transported via tumor-released EVs include TGF-β, caveolin-1, HIF1α and β-catenin, all of which were shown to promote EMT, extracellular matrix remodeling and metastatic niche formation." (PMID 33348923, 2020). "HIF-1α and its key transcriptional target, VEGF, are the main factors mediating tumor growth and angiogenesis." (PMID 33424993, 2020). "26, 27 Moreover, a PC in vivo experiment suggested that salidroside suppressed tumor growth, increased cell apoptosis, inhibited the metastasis of BxPC‐3 cells to the lung, and reduced HIF‐1α, LOXL2, MMP2, and MMP9 while enhanced E‐cadherin in tumor tissue." (PMID 31162697, 2020). "In summary, this study provides novel insight showing that hypoxia-induced HIF1α mediates GBE1 upregulation, which suppresses FBP1 expression by promoter methylation via NF-κB signaling in the tumor microenvironment of LUAD." (PMID 32439898, 2020). "Overall, hypoxia‐induced expression of OTUD6B increased stability of pVHL, which recognizes hydroxylated or SUMOylated HIF‐1α under hypoxia, and leads to rapid polyubiquitylation and proteasomal degradation of HIF‐1α and suppressed tumor metastasis." (PMID 32328410, 2020). "After treatment with Nb@IC-NPs, the HIF-1α fluorescence signal was reduced significantly, demonstrating Nb@IC-NPs could effectively overcome hypoxic characteristic of cell-to-tumor, and this is the key to improving tumor hypoxia microenvironment and promoting PDT." (PMID 33292202, 2020). "Stable expression of HIF-1α and HIF-2α was detected in most RCC tissues in 11 pairs of matched renal normal-tumor samples, but was only observed in Caki-1 cells; therefore, these cells were used for further mechanistic studies." (PMID 32206108, 2020). "Hypoxia inducible factor-1α (HIF-1α) plays a major role in HIF-1-induced gene expression under hypoxic conditions and undertakes an “angiogenic switch” function during tumor metastasis." (PMID 31963946, 2020). "Targeting HIF-1α, therefore, can have a therapeutic potential in HCC through the interruption of tumor angiogenesis." (PMID 32516967, 2020).
tumor (continued). "Recently, it was also found that HIF-1α mediated protein kinase C(PKC)-induced upregulation of glycolytic genes, thereby promoting tumor cell proliferation in prostate cancer cells." (PMID 32928258, 2020). "Subsequent in vitro and in vivo experiments suggested that RICTOR blockade impaired tumor growth via decreasing the activation of the AGC kinase and decreasing the expression of hypoxia-inducible factor 1-alpha (HIF-1α) and VEGF-A." (PMID 32041519, 2020). "HIF-1α, an active subunit of HIF-1, which is essential for tumor cells to adapt to a low-oxygen environment, has a vital role in aerobic glycolysis and tumorigenesis." (PMID 32454874, 2020). "We then compared the protein expression (digital H-score) of HIF1α, VEGF, and bFGF among the four cellular compartments within MBM tumor samples." (PMID 33552976, 2020). "In renal carcinogenesis, HIF-1α functions more as a tumor suppressor than a tumor promoter, whereas HIF-2α is deemed to predominantly promote tumor growth and angiogenesis." (PMID 33510766, 2020). "Overexpressed circ-0000977 serves as a sponge for miR-153 to counteract miR-153-mediated suppression of HIF-1α and ADAM10, promoting the shedding of membrane MICA (mMICA) from surface of tumor cells and converting into soluble MICA (sMICA)." (PMID 32587480, 2020). "HIF-1α not only inhibits pyruvate metabolic pathway in mitochondria during glycolysis, but also inhibits fatty acid oxidation (FAO) to promote tumor progression." (PMID 33109235, 2020). "Moreover, cellular immunofluorescence and immunohistochemistry experiments proved that the IQuCS@Zr-PEG NSPs can downregulate the expression of HIF-1α under MW irradiation, and reflected the reoxygenation of tumor cells from the side, which maybe the key factor for the high tumor inhibition rate." (PMID 32292521, 2020). "We here find that CEP41 facilitates hypoxia‐induced angiogenesis through HIF1α‐AURKA‐VEGF pathway in vitro and further show that CEP41 affects EC dynamics under tumor‐induced hypoxic conditions in vivo." (PMID 31885126, 2020). "VEGF, one of the target genes of HIF-1α, was increased after exposure to IR or hypoxia, and inhibiting VEGF or VEGFR were effective strategies for improving the tumor radiosensitivity in clinical studies." (PMID 32403326, 2020). "Mechanistically, NHWD-870 reduces the expression and secretion of macrophage colony stimulating factor 1 (CSF1) in tumor cells by blocking the functional activity of BRD4 and its target gene HIF-1α." (PMID 33109235, 2020). "It is well known that, the three ubiquitinated substrates of FBX8, HIF-1α, CDK4 and C-Myc, are closely related to tumor progression." (PMID 32796813, 2020). "SIX4 also intensified VEGF-A expression by coordinating with HIF-1α in CRC, promoting angiogenesis and tumor growth both in vivo and in vitro." (PMID 33276489, 2020). "In hypoxic tissues, such as the tumor microenvironment, there is a reciprocally synergistic relationship between MIF and HIF-1α; hypoxia-driven HIF-1α stabilization and subsequent transcriptional regulation promotes an enhanced expression of MIF." (PMID 33324425, 2020). "The distinct roles of HIF-1α and HIF-2α cover the regulation of cell differentiation and promotion of the tumor cell resistance and invasion." (PMID 32878021, 2020). "SAB induced apoptosis and inhibited tumor cells angiogenesis by inhibiting expression of Cox-2, HGF, MMP-2, HIF-1α, TNFα, MMP-9, tenascin, osteopontin as well as transforming growth factor (TGF)-1β and up-regulating the level of THBS-2." (PMID 36046777, 2020). "Despite a fundamental understanding of the cellular response to hypoxia as orchestrated by the hypoxia-inducible transcription factors (mainly HIF-1α and HIF-2α), hypoxia-induced tumor aggressiveness is only partially understood." (PMID 32205867, 2020).
tumor (continued). "More interestingly, upon administration of bevacizumab via intratumoral injection, the tumor cells highly expressed GFP, HIF1α and IL-8; and furthermore, a greater number of cells were GFP+ cells, suggesting that TBe were more hypoxic than TPBS." (PMID 32737283, 2020). "HIF-1α activity up-regulates VEGF expression in hypoxic tissues, making HIF-1α essential for wound regeneration and tumor vascularization." (PMID 31903130, 2020). "This study defines differing roles of HIF-1α and HIF-2α in ccRCC formation and progression and suggests a model in which alterations in their relative activities affect different aspects of tumour biology and immunology." (PMID 32807776, 2020). "In fact, ZEB1 is known to be activated by hypoxia inducible factor 1-alpha (HIF-1α), a master transcriptional regulator of many responses in tumor invasion." (PMID 33097763, 2020). "The metabolic switch to glycolysis in tumor cells is controlled by glycolysis-related enzymes (GLUT1, LDHA, ALDOB) and vital signaling pathways (PI3K-AKT, mTOR, Myc, HIF-1α)." (PMID 33244454, 2020). "A high dose of CLG inhibited the growth of transplanted tumor and liver metastasis of CRC in nude mice, probably by inhibiting the HIF-1α/SDF-1α-CXCR4/PI3K-Akt signaling pathway reducing the synthesis and release of VEGF and degradation of collagen IV." (PMID 30789971, 2019). "Because of varying multiple parameters simultaneously, effect of any single parameter on the levels of HIF-1α, HIF-2α and tumor progression cannot be inferred accurately as of now." (PMID 31382593, 2019). "The hypoxia-induced, hypoxia-inducible factor-1 alpha (HIF-1α)-dependent expression of CD73 and ADORAs in tumor cells and host cells make CD73 and adenosine promising targets particularly for tumors with pronounced hypoxia, high HIF-1α–expression, or both." (PMID 31623231, 2019). "Taken together, mounting evidence implicates both HIF-1α and HIF-2α proteins in a highly context dependent but orchestrated manner in tumor cell survival, hypoxia tolerance and treatment response." (PMID 30642030, 2019). "During normoxic conditions, prolyl-hydroxylases (PHDs) hydrolyze HIF-1α, which can then be recognized by the von Hippel–Lindau (VHL) tumor suppressor." (PMID 31354653, 2019). "In this study, we observed that BEZ235 and RT treatments followed by BEZ235 maintenance treatment significantly downregulated VEGF-A and HIF-1α expression in CRC cell lines and xenograft tumor tissue." (PMID 31430901, 2019). "The decreased expression of Hif-1α and its downstream effectors, including HK1, HK2, PKM1, and PKM2 in PD901 treated tumor cells was further confirmed by Western blotting (Sup." (PMID 30741922, 2019). "Previously, we have shown that CHCHD4 regulates HIF-1α protein induction and HIF signalling in hypoxia and is required for tumour growth in vivo." (PMID 30886710, 2019). "Data showed that blocking the HIF-1α pathway by 2-MeOE2 dramatically reduced tumor volume and weight formed by HCT116 PTBP3 OE cells, highlighting HIF-1α as a critical effector of PTBP3-mediated malignant features." (PMID 31291975, 2019). "In vivo experiment validated that miR-199a functioned as a tumor suppressor, inhibited tumor growth by targeting K-RAS and suppressed activation of AKT, ERK and HIF-1α expression." (PMID 31681604, 2019). "CA can also act on angioneogenesis of HCC tumor cells by reducing the phosphorylation of JNK-1 (c-Jun N-terminal kinases, a member of the MAPKs family), via decreasing the activation of HIF-1α (Hypoxia Inducible Factor 1)." (PMID 31293975, 2019). "These in vitro data explain why levels of Bclaf1, HIF-1α, and HIF-1α targets positively correlate with each other in clinical HCC samples, and also correlated with tumor weight in a xenograft HCC tumor model." (PMID 30367150, 2019). "Our results showed that UTMD-mediated HIF-1α shRNA transfection and TAE can obviously silence HIF-1α and VEGF expression, thereby successfully inhibiting the growth of the tumor." (PMID 30911540, 2019).